CHD1 (chromodomain helicase DNA binding protein 1)
Diseases named in the same sentence as CHD1 in open-access papers (continued):
Sharing a sentence is not in itself a finding about the gene and the disease.
cancer (45 papers, 2011 to 2026). A tumor composed of atypical neoplastic, often pleomorphic cells that invade other tissues. "This study reveals how a cancer-associated mutation in CHD1 leads to the loss of its C-terminal intrinsically disordered region, disrupting condensate formation." (PMID 41168190, 2025). "Among the YTHDC2 associated and cancer-related genes (CRGs), CHD1 regulates WNT signaling, EMT and pluripotency genes like SOX2 and NANOG." (PMID 41145440, 2025). "Dysfunctions and mutations in the CHD1 gene have been linked to cancer and neurodevelopmental disorders." (PMID 41168190, 2025). "Here, we examine the role of the E1321 frameshift mutation in CHD1, a chromatin remodeler, which is often targeted in cancers." (PMID 41168190, 2025). "Among these components, MLL mutations frequently co-occur with CHD1 mutations in various cancers, suggesting a shared pathway in cancer development." (PMID 41168190, 2025). "Prompted by the remarkable overlap in ASH2L and CHD1 target genes, we examined their loss-of-function in diverse cancer types and found mutations in CHD1 and histone lysine methyltransferases of the MLL complexes frequently co-occurred." (PMID 41168190, 2025). "Given that CHD1 is upregulated and plays an essential role in PTEN-deficient cancers, we also discuss the therapeutic potential of targeting CHD1 and its downstream effectors in tumors containing PTEN deficiency." (PMID 36776288, 2023). "The expression of CHD1 is modulated at both post-transcriptional and post-translational levels, and its dysregulation is associated with cancer development and other human diseases." (PMID 36776288, 2023). "Functionally, we identified CHD1 as a synthetic essential gene in cancers containing PTEN deficiency." (PMID 36776288, 2023). "Combining high-throughput epigenetic screening and pan-cancer drug sensitivity analyses, we reported that CHD1 promotes the susceptibility of cancer cells to inhibitors targeting Aurora kinases." (PMID 36776288, 2023). "In our recent study, we uncovered that CHD1 loss impaired the in vitro and in vivo efficacy of Aurora kinase inhibitors, while high expression of CHD1 is associated with increased sensitivity in a pan-cancer manner." (PMID 36776288, 2023). "Of note, despite only 259 cases with metastasis, CHD1 deletion was also statistically linked to MFS in our set of data; likewise, CHD1 deletion was linked to CSS despite only 124 cases with confirmed cancer-specific death." (PMID 33414516, 2022). "PTEN-deficient cancers are known to have synthetic essential relationships with CHD1 and PDHK117,18." (PMID 34535684, 2021). "High BCAR1 staining was associated with PTEN deletion (p < 0.0001) and marginally associated with deletions of CHD1 (5q21) (p = 0.0084) when all cancers were jointly analyzed." (PMID 29304771, 2018). "Much has been made of determining the right medication for the right person (eg, warfarin dosing for those with a CYP [cytochrome P450] mutation) or when to start cancer screening based on genetic profiles (eg, colorectal screening for CHD1 [chromodomain helicase DNA binding protein 1])." (PMID 39916376, 2025). "Moreover, folate status has also been increasingly associated with CHD1-linked pathways in cancers such as adenomatous polyposis coli/wingless (APC/WNT) pathway." (PMID 39025327, 2024). "Along with epigenetic modifiers that were previously implicated in cancer cell fitness, such as CHD1, CHD4, DNMT3B, ELP3, SUPT16H, SUV39H2; novel hits ASH2L, RBX1 and SSRP1 were discovered as essential genes for both U373 and T98G cells suggesting common regulatory role." (PMID 37974198, 2023).
cancer (continued). "Essentiality of chromatin remodeling factor CHD1 is demonstrated in PTEN-deficient cancer." (PMID 37974198, 2023). "Whereas this order may result in cell survival advantages for specific alterations at distinct stages of cancer progression, loss of specific genes such as CHD1 may directly contribute to an increase in copy number burden." (PMID 36059000, 2022). "Interestingly, Chd1-deficient human cancer cells have defective DNA repair when exposed to ionizing radiation or radiomimetic chemicals." (PMID 34381042, 2021). "This may account for the global gene expression changes seen in cancers with CHD1 mutations." (PMID 41168190, 2025). "CHD1 and MAP3K7 are recurrently mutated in cancer, and reduced expression in tumors correlates with response to immune checkpoint inhibitors in patients, nominating these genes as potential biomarkers of immunotherapy response." (PMID 41564866, 2026). "Extending these insights, our results suggested that CHD1 may regulate genes associated with platinum sensitivity and cell migration, making the development of selective CHD1 inhibitors or degraders a promising precision therapeutic strategy for R175G mutation cancers." (PMID 41249788, 2025). "Intersection analysis of YTHDC2-associated genes with the Catalogue of Cancer Genes (CCG) revealed several cancer-related genes, such as DMXL1, CHD1, and APC, showing strong positive association with YTHDC2 expression." (PMID 41145440, 2025). "This knowledge lays an important foundation for developing effective therapeutics targeting the dysregulated CHD1 in cancers and using CHD1 as a biomarker for predicting the response to therapies." (PMID 36776288, 2023). "Several independent groups are dedicated to developing small-molecule inhibitors targeting CHD1, and the efficacies of top hits will be tested in cancer cell lines and diverse preclinical models." (PMID 36776288, 2023). "In the past decade, we have gained a better understanding of CHD1 biology and how its dysregulation impacts cancer development and progression." (PMID 36776288, 2023). "Transcriptomic and epigenetic profiling studies in ESCs and cancer cells showed that CHD1 is required for sustaining the opening of chromatin and the global transcription." (PMID 36776288, 2023). "In either scenario, Chd1 activity at transcribed promoters protects genome integrity, a finding with significant implications in stem cell biology and cancer." (PMID 34381042, 2021). "Some TFs in the module have been demonstrated to involve in cancer procession, such as CHD1, NFAT5, and POU2F1." (PMID 34513699, 2021). "EMT involves expression modulation of several genes, including CHD1, which encodes E-cadherin, one of the most important markers of EMT in several types of cancer, including NB." (PMID 32825087, 2020). "We considered the cohesin complex and the CHD1 deletion that is found in many cancers, and that is particularly frequent in PCA." (PMID 31222142, 2019). "In ERG-negative cancer, high levels of BCAR1 expression were significantly linked to presence of deletions of PTEN (p < 0.0001), CHD1 (5q21) (p < 0.0001) and MAP3K7 (6q15) (p < 0.0001), while these associations were lost in ERG-positive cancer." (PMID 29304771, 2018). "We found that CHD6 and CHD7 were the most commonly gained/amplified or mutated, whereas CHD1 and CHD3 were the most deleted CHDs in a spectrum of human cancers." (PMID 28649742, 2017). "We found that CHD6 and CHD7 were most commonly gained/amplified or mutated, whereas CHD1 and CHD3 were most deleted in a spectrum of human cancers." (PMID 28649742, 2017). "Tumors with high rearrangement frequencies often have two genes deleted from their cells: the MAP3K7 gene, which is deleted in 30–40% of tumors; and the CHD1 gene, which is deleted in 15–20% of cancers." (PMID 26506153, 2015).
cancer (continued). "Cancer cells have been shown to utilize NMD, for example via actions on mutant cadherin transcripts (Chd1) that are associated with poor clinical outcome in hereditary diffuse gastric cancer." (PMID 23359859, 2013). "Here, we showed that the E1321 frameshift (fs) mutation of CHD1, frequently found in cancers, produces a truncated protein lacking its C-terminal intrinsically disordered region (IDR)." (PMID 41168190, 2025). "Thus, ESS2-dependent alterations in CHD1 recruitment can regulate genome-wide gene expression in cancer." (PMID 37524814, 2023). "In addition, we highlight the differential therapeutic strategies for cancers harboring CHD1 defects or overexpression." (PMID 36776288, 2023). "Although considerable interest in the prognostic and therapeutic potential of CHD1 deletion in PCa is currently growing, the potential implications of CHD1 deletion for distant metastasis formation that are responsible for cancer-specific death in PCa patients remain to be determined." (PMID 33414516, 2022). "In addition, six tumor suppressor genes previously implicated in cancer (BTK, CHD1, FN1, NFATC2, NOTCH1, and NRP1) were found in at least two samples." (PMID 34489456, 2021). "CHD1 was also reported to be a tumor suppressor gene in many human cancers." (PMID 28694563, 2017). "Given that CHD1 may affect DNA repair, and that the loss of the closely related CHD4 protein makes it easier for PARP inhibitors to kill cancer cells, such a model may provide mechanistic insights that focus future therapeutic approaches." (PMID 26506153, 2015). "However, the precise mechanisms through which CHD1 abnormalities contribute to cancer development remain unclear." (PMID 41168190, 2025). "In addition to these key driver genes, our analysis has also identified CCND2 and CHD1, which are known to be involved in various types of cancer but have not previously been linked to DN or T2D." (PMID 38966710, 2024). "Furthermore, we highlight the potential therapeutic strategies for cancers with dysregulated CHD1." (PMID 36776288, 2023). "Interestingly, unlike LUAD, the decrease in CHD1/2 mRNA expression levels in LUSC was significantly associated with cancer stage." (PMID 35467222, 2022). "In the subset of patients with CHD1 deletion, the incidence of BCR, metastasis, and cancer-specific death increased to 31.3%, 7.8%, and 3.1%, respectively." (PMID 33414516, 2022). "SPOP-mutant cancers generally lack genetic alterations in the PIK3 pathway but show a distinct pattern of genomic alterations, including losses of CHD1 at 5q21, 2q, and 6q." (PMID 29581876, 2018). "In summary, among nine CHD genes, CHD6 and CHD7 had the highest frequency of genetic gain/amplification, whereas CHD1 and CHD3 were most commonly deleted in a spectrum of human cancers." (PMID 28649742, 2017). "CHD1 and CHD2 chromatin remodeling enzymes play important roles in development, cancer and differentiation." (PMID 25621013, 2015). "On the other hand, the cancer cells with an overexpression of hPaf1/PD2 and CHD1 have active transcriptional upregulation and, as a result, chromatin rearrangement occurs, constantly making the chromatin template less accessible to nuclease digestion." (PMID 22046413, 2011). "No linkage between CHD1 and CDK12 mutations and cancer progression has been observed in our cohort except for the germline variant P1275L in CDK12 that will be discussed later." (PMID 35347810, 2022). "Moreover, CHD1 deletion predicts shortened BCR-free survival in pT2 patients and cancer-specific survival in all patients." (PMID 33414516, 2022).
cancer (continued). "As the 5q21 (CHD1) deletion is mainly occurring in ERG fusion‐negative cancers, we next analyzed PSA recurrence in the subsets of 5q21‐normal (n = 5835) vs. 5q21‐deleted (n = 658) patients." (PMID 33533127, 2021). "LPD5 cancer samples exhibited exactly the reverse pattern of genetic alteration: there was under-repression of ETS and PTEN gene alterations, and over-representation of SPOP and CHD1 alterations." (PMID 32203215, 2020). "Altogether, these results imply that CHD1 and PDS5 cooperate in cancer development." (PMID 31222142, 2019). "Among nine CHDs, CHD1 and CHD3 were most commonly deleted in a spectrum of human cancers." (PMID 28649742, 2017). "The other known drivers of the PCa early development (in fusion-negative cancers) are also several: SPOP mutation, SPINK overexpression, CHD1 deletion and TAK1 loss, as well as chromosomal losses not characterized in terms of genes involved." (PMID 25277175, 2014).
infection (6 papers, 2009 to 2024). The state of being infected such as from the introduction of a foreign agent such as serum, vaccine, antigenic substance or organism. "Collectively, our data provide evidence that intestinal resistance against infection by P. aeruginosa in Drosophila is linked to maintaining proper balance of gut-microbe interactions and that the chromatin remodeler CHD1 is involved in regulating this aspect." (PMID 22912810, 2012). "Alternatively, CHD1 might act indirectly, for instance by causing deregulation of gut physiology or developmental processes, which in turn may favour microbiome changes and/or affect susceptibility to infection." (PMID 27093431, 2016). "Second, IL-10-induced JMJD2A and CHD1 can encourage genes desired in the regeneration of tissues after infection and prevent neutrophils from LPS-activation or TNF-preactivation." (PMID 38745328, 2024). "RNAi knockdown of either CHD2 or the related CHD1 protein, in human cells resulted in a block to infection by HIV-1, specifically at the level of transcription." (PMID 25297984, 2014). "About 50% of Chd1-mutant flies had succumbed to the infection after 5 days, and less than 5% were alive after 14 days compared to 80% of the Chd1WT/WT line." (PMID 22912810, 2012). "To examine, if cell damage occurs upon infection in Chd1−/− guts, we performed immunostainings with antibodies against activated caspase 3 but were unable to detect increased cell death in the guts of Chd1−/− flies (data not shown)." (PMID 22912810, 2012). "10–15 days after shRNA infection and puromycin selection, the percentage of Spt6 and Chd1 knocked-down cells expressing GFP reached ca. 5%, a significantly higher proportion that obtained with a control shRNA vector." (PMID 19148280, 2009). "Reduced infection in this case was associated with a decrease in CHD1 mRNA levels, as CHD2 mRNA was not depleted in these experiments." (PMID 25297984, 2014). "However, in Chd1 mutant intestines P. aeruginosa showed 25 fold higher enrichment after 3 days of infection and ∼100 fold enrichment after 4 days of infection compared to wild-type guts." (PMID 22912810, 2012). "We observed that loss of CHD1 rendered flies susceptible to infection by the gram-negative bacterium Pseudomonas aeruginosa upon ingestion of the bacteria but did not affect sensitivity upon septic injury." (PMID 22912810, 2012). "Alternatively or in addition to the explanations proposed above for the effect of Chd1 deletion on AMP expression and fly survival upon infection, it is possible that CHD1 contributes to maintaining the fly intestine in a state that will allow for efficient combat of invading pathogens." (PMID 22912810, 2012). "Next we determined whether CHD1 is required for the regulation of AMP gene expression upon infection." (PMID 22912810, 2012). "Infection experiments using different microbial species revealed defects in host defense in Chd1-deficient adults upon oral infection with P. aeruginosa but not upon septic injury, suggesting a so far unrecognized role for CHD1 in intestinal immunity." (PMID 22912810, 2012). "Thus, in sharp contrast to oral infection, where loss of Chd1 renders flies susceptible to infection, CHD1 does not appear to impact on the systemic immune response." (PMID 22912810, 2012). "There were three common DE genes between cattle and sheep at the acute stage of infection: IL1RL1, CHD1 and RASSF1, and 232 common DE genes at the chronic stage of infection." (PMID 34616397, 2021). "These experiments revealed that the absence of CHD1 severely hampered survival of the flies after infection with P. aeruginosa." (PMID 22912810, 2012). "Intriguingly, gut-specific expression of AttC, DipB, Mtk and dro3 was significantly overactivated in adult Chd1−/− mutant flies in the absence of infection." (PMID 22912810, 2012).
infection (continued). "The facts that we find considerably elevated bacterial titers in the guts of Chd1−/− flies in the absence of infection as well as the strong enrichment of P. aeruginosa outside the gut upon infection are in good agreement with such a scenario." (PMID 22912810, 2012). "Further molecular analysis showed that gut-specific transcription of antimicrobial peptide genes was overactivated in the absence of infection in Chd1 mutant flies." (PMID 22912810, 2012). "Interestingly, we found profoundly increased titers of bacteria in dissected guts from Chd1−/− flies in the absence of P. aeruginosa ingestion as well as after infection." (PMID 22912810, 2012). "Interestingly, these experiments did not reveal evidence that Chd1−/− flies were more sensitive towards infection than the rescued line." (PMID 22912810, 2012). "Together these results indicate that CHD1 most likely does not impact on the induction of AMP expression in response to bacterial challenge, but that it contributes to the maintenance of proper AMP levels in the absence of infection." (PMID 22912810, 2012).
neurodevelopmental disorder (6 papers, 2021 to 2026). A behavioral and cognitive disorder with onset during the developmental period that involves impaired or aberrant development of intellectual, motor, or social functions. "Loss of Chd1 increases seizure susceptibility and disrupts motor function, mirroring phenotypes observed in CHD2-related neurodevelopmental disorders." (PMID 41833011, 2026). "In a recent genetic study of CHD1,2, de novo mutations were estimated to contribute to 10–30% of syndromic cases who had additional congenital anomalies or neurodevelopmental disorders (NDD), but only about 4% of isolated cases who did not have additional anomalies or NDD." (PMID 33479230, 2021).
hematologic malignancies (1 paper, 2020). "Some of these hub genes were either considered essential to the survival of AML cells (JMJD1C) or identified as fusion partners (CHD1) of the major player in hematologic malignancies (RUNX1)." (PMID 31988326, 2020).
CHD1 also shares sentences with these, for which no sentence is quoted: Intellectual disability (2 papers); ovarian carcinoma (2); acute myeloid leukemia (1); adenocarcinoma (1); Anxiety (1); autism (1); autism spectrum disorder (1); chronic intestinal pseudo‐obstruction (1); colon cancer (1); Epileptic encephalopathy (1); leukemia (1); lung disease (1); metastatic colorectal cancer (1); myocardial infarction (1); neuroblastoma (1); orofacial cleft (1); Pilarowski-Bjornsson Syndrome (1); RASopathies (1); sarcoma (1); Seizure (1); Speech apraxia (1); stomach cancer (1); triple-negative breast carcinoma (1).